INS (insulin)
Diseases named in the same sentence as INS in open-access papers (continued):
Sharing a sentence is not in itself a finding about the gene and the disease.
cardiovascular disease (continued). "The currently reported study was therefore undertaken to evaluate the effects of Px therapy on insulin responsiveness in patients with stable T2D and cardiovascular disease, and to determine whether its effects on insulin signaling might parallel changes in tissue responsiveness to NO." (PMID 36289640, 2022). "In addition, the results from this study and a search of the literature suggest that the use of other markers such as fasting insulin, triglycerides and waist-hip ratio as illustrated by the ISI-cal index are in keeping with identifying asymptomatic individuals at risk of cardiovascular disease." (PMID 36352897, 2022). "Furthermore, a clinical trial showed that resistance exercise training could improve glucose tolerance and enhance insulin action in skeletal muscle to reduce the incidence of cardiovascular disease." (PMID 35769791, 2022). "The randomized, placebo-controlled trial hyperinsulinemia: the outcome of its metabolic effects (HOME) was designed to investigate whether treatment with metformin, in addition to insulin for glycemic control, could decrease cardiovascular disease in established diabetes patients." (PMID 35379238, 2022). "The protective effect of moderate alcohol consumption on cardiovascular disease in the general population was previously assumed to be due to alcohol-associated increases in HDL cholesterol and apolipoprotein A1 levels, increased insulin sensitivity, and reduced platelet aggregation." (PMID 35707634, 2022). "Participants with an elevated FLI were more likely to have higher age, T2D, a history of cardiovascular disease, a history of malignancy, higher blood pressure, lower NT‐ProBNP, lower alcohol intake, lower eGFR, higher urinary albumin excretion, higher glucose and higher insulin (all P < .05)." (PMID 34120339, 2021). "On the other hand, the ectopic deposition of fats, which is causative of cardiovascular diseases, may also occur regardless of glucose/insulin tolerance." (PMID 32478098, 2020). "This hypothesis can be further supported by data recently published showing that in people with cardiovascular disease and/or CV risk factors, insulin glargine used to target normoglycemia modestly reduced carotid IMT progression." (PMID 25300286, 2014). "The more overweight/obese the persons are, the more likely they are to be insulin-resistant and at increased risk of cardiovascular disease, but substantial numbers of overweight/obese individuals remain insulin-sensitive, and not all insulin-resistant persons are obese." (PMID 19936118, 2009). "This oxidative stress contributes to β-cell dysfunction and impaired insulin secretion, which are central to the development and progression of T2DM and its complications, including increased risks of cardiovascular disease and premature mortality." (PMID 40525136, 2025). "The disease is characterized by defective insulin secretion (INS) or IR, and long-term hyperglycemia can lead to serious complications such as cardiovascular disease, nephropathy, retinopathy, etc., which greatly threaten human health." (PMID 40363788, 2025). "Along with the manifested inflammation in T2DM, oxidative stress-induced dysfunction of the endothelium makes the cells resistant to the hormone insulin and the eventual progression of T2DM and cardiovascular disease." (PMID 39544568, 2024). "The authors identified male sex, age >65, pre-existing comorbidities, including cardiovascular diseases, CKD, COPD, prehospital insulin use, and blood glucose on admission ≥11 mmol/l to be associated with the investigated outcome." (PMID 36844106, 2023). "Patients of T2DM in the HbA1c > 7% group had markedly higher levels of FBS, fasting insulin, HOMA-IR, TGI, THR and cardiovascular disease (CVD) events, Table-I." (PMID 37680799, 2023). "Insulin has been identified to promote VSMC proliferation and migration; resveratrol has been shown to have protective effects against cardiovascular diseases." (PMID 36479179, 2022).
cardiovascular disease (continued). "The high incidence of cardiovascular diseases (CVD) and diabetes have led to huge market demand for insulin (and insulin-like) molecules." (PMID 34976961, 2021). "While we did not specifically evaluate insulin sensitivity in the present study, it is interesting to note that our most “at-risk” bariatric surgery candidate (according to medication use, BMI, and cardiovascular disease risk factors) had the lowest CVR by almost 2 standard deviations." (PMID 32082607, 2020). "First, we analyzed plasma of 955 subjects involved in the Relationship between Insulin Sensitivity and Cardiovascular Disease (RISC) Study using the validated oral glucose insulin sensitivity (OGIS) index as a marker of glucose clearance." (PMID 29246479, 2018). "In patients already presenting with cardiovascular disease, the best outcome may be expected with the triple oral therapy of metformin, pioglitazone, and empagliflozin, although a controlled prospective study versus insulin therapy is needed to confirm the expectation." (PMID 27071968, 2016). "We summarize here the current knowledge about the influence of adiponectin on insulin sensitivity and endothelial function, discussing its forthcoming prospects and potential role as a therapeutic target for MS, T2DM, and cardiovascular disease." (PMID 24957699, 2014). "Comparison between men and women showed that men had higher age, Cr, eGFR, FPG, TG, SBP, WC, smoking rate, family history of cardiovascular disease and lower BMI, HDL-C and baseline insulin level than women." (PMID 24086723, 2013). "Therefore, cardiovascular disease may be caused by insulin resistance rather than being a consequence of the toxic effects of elevated insulin or glucose concentrations." (PMID 23300589, 2012). "South Asian Americans are generally more insulin resistant, have elevated CRP concentrations and more cardiovascular diseases despite sharing the similar feature of low BMI with East AA." (PMID 22164267, 2011). "Excess sugar consumption, specifically fructose, directly precipitates cardiovascular disease by dysregulation of lipid, carbohydrate, and insulin homeostasis independent of excess weight." (PMID 37467045, 2023). "Confounding factors pose a challenge as not all studies excluded patients with cardiovascular disease and only some considered insulin/hyperglycemic drugs." (PMID 38089605, 2023). "There was a substantial rise in BMI, FBG, HbA1c, HDL-C, and insulin among diabetics with cardiovascular disease compared to diabetics without cardiovascular disease (p-value = 0.001, 0.000, 0.018, and 0.000)." (PMID 39450303, 2022). "Obese children with a more significant alteration in insulin sensitivity are at greater risk of developing T2DM and cardiovascular diseases, compared with peers without IR, given the same BMI." (PMID 35069452, 2021). "Many prospective studies in nondiabetic subjects have found that elevated insulin levels, either fasting or in response to oral glucose, have a predictive role in the development of cardiovascular disease." (PMID 34360563, 2021). "Further adjustment for potential confounders, including history of cardiovascular disease, history of malignancy, T2D, glucose, insulin and use of glucose‐lowering drugs, did not materially change the associations." (PMID 34120339, 2021). "This prospective, randomized, and multicenter study included 282 insulin-treated subjects without a history of overt cardiovascular diseases and observed the effects of sitagliptin for 2 years." (PMID 33322512, 2020). "In a previous study in Catalonia, the prevalence of non-initiation one month after prescription of insulin and treatments for cardiovascular disease was estimated to range from 7.5% through 13.17%." (PMID 32408626, 2020). "A great proportion of them was not insulin dependent, they were on treatment for cholesterol and blood pressure but did not have any complications of the disease nor had they a cardiovascular disease." (PMID 33271823, 2020).
cardiovascular disease (continued). "In participants with no cardiovascular disease, an inverse relationship was noted between magnesium and fasting serum insulin, glucose, systolic blood pressure, and smoking." (PMID 29075585, 2017). "IR is a condition in which the normal insulin level fails to promote glucose homeostasis, favoring the development of metabolic and cardiovascular diseases." (PMID 27490249, 2016). "Both short and long-acting insulin analogues (AI) have been shown to reduce glucose variability and provide potential benefit for cardiovascular disease although the effects on cardiac function have not yet been evaluated." (PMID 26772807, 2016). "The first model included Sprague Dawley (SD) rats that developed NAFLD without IR, and the second one included a rat model of genetic IR and cardiovascular disease, the spontaneously hypertensive rats (SHR) and its normotensive, insulin-sensitive control Wistar-Kyoto (WKY)." (PMID 24098813, 2013). "This is despite the advances in insulin delivery with insulin analogues and continuous subcutaneous insulin infusion (CSII), highlighting the need to identify additional vascular protective strategies to prevent cardiovascular disease at its inception." (PMID 23865839, 2013). "Notably, unlike the beneficial insulin sensitizing function in adipose tissue, the role of PPARγ in cardiovascular disease remains controversial." (PMID 38280036, 2024). "However, when systematically assessing the risk factors of MUO, a clear tendency towards the importance of the parameters of insulin resistance and glucose metabolism rather than inflammation, lipid metabolism or cardiovascular disease can be seen." (PMID 37371690, 2023). "It has been further revealed that the protective effects of pioglitazone on cardiovascular disease may be induced by increased insulin sensitivity and improved IR, rather than decreased blood glucose." (PMID 36312238, 2022). "Overexpression of miR-223 increases GLUT4 levels and inhibits insulin-stimulated AKT and GSK3β phosphorylation, while the overexpression of miR-133 decreases GLUT-4 levels, demonstrating their implication in IR and metabolic control in the heart and during cardiovascular disease." (PMID 35204710, 2022). "We next investigated if loss of IGFBP-1 influences vascular function, recognizing that several studies report a negative correlation between IGFBP-1 and biomarkers of cardiovascular disease such as blood pressure, BMI, waist/hip ratio, and fasting insulin levels." (PMID 32190801, 2020). "However, it seems that moderate alcohol consumption may be beneficial in the prophylaxis of T2DM and cardiovascular diseases, which is probably due to increased serum HDL-C and reduction in fasting glucose levels and HbA1c, and increased insulin sensitivity." (PMID 33171835, 2020). "However, in another study, no seasonal difference in fasting insulin was demonstrated in 100 adults with cardiovascular disease." (PMID 31623384, 2019). "Raised non-esterified fatty acids impair insulin’s effect on glucose uptake in skeletal muscle and could thus have detrimental effects on the vascular endothelium, which leads to premature cardiovascular disease." (PMID 29636047, 2018). "Since, the adverse clinical outcomes in patients with Insulin-Treated Type 2 Diabetes Mellitus (ITDM) implanted with DES and BMS have not been previously studied, we aim to compare the clinical outcomes in similar patients with cardiovascular diseases, treated with DES and BMS." (PMID 27111304, 2016). "A clear limitation is the lack of information on glomerular filtration rate and serum insulin, since these variables could be affected in patients with cardiovascular disease, and they can also affect the level of SUA." (PMID 23533601, 2013).
cardiovascular disease (continued). "This may ameliorate early identification of individuals who are candidates for appropriate therapeutic interventions aimed at addressing the twin epidemic of metabolic and cardiovascular disease in settings where more extended testing such as insulin assays are not feasible." (PMID 33859227, 2021). "The biochemical differences between people with and without cardiovascular disease shown inTable 2, there were significant increases in FBG, HBA1c, TG, HDL-c, and insulin between the two groups with p values 0.05, but no significant statistical difference in TC and LDL-c with p values > 0.05." (PMID 39450303, 2022). "In multivariate analysis, compared with the multimorbidity-free, patients with cardiovascular disease patterns (Class1) had greater BMI (OR [95 % CI]: 2.52 [1.35,4.70]) and LDL (OR [95 % CI]: 1.27 [1.00,1.60]), and were more likely not to be treated with insulin (OR [95 % CI]: 2.19 [1.29,3.73)." (PMID 40084007, 2025).
infection (648 papers, 2000 to 2026). The state of being infected such as from the introduction of a foreign agent such as serum, vaccine, antigenic substance or organism. "Earlier studies suggested that the insulin/IGF-1 signaling pathway has been involved in conferring resistance against pathogenic infections." (PMID 40401953, 2025). "Injectable hydrogels serving as insulin delivery systems offer many advantages, such as less frequent injections, bypassed first-pass metabolism, reduced risk of tissue infection, and localized insulin amyloidosis." (PMID 40292663, 2025). "In recent years, pulmonary insulin delivery has emerged as an alternative approach for overcoming the therapeutic disadvantages of subcutaneous insulin administration, such as pain, infection risk, and needle phobia." (PMID 40703749, 2025). "It is possible that the upregulation of this antiviral pathway due to the loss of the insulin-regulator Lst contributes to decreased susceptibility to infection in LstMI06290 mutant flies." (PMID 38921161, 2024). "DKA results from insulin deficiency due to inadequate insulin administration, infection, surgery, or drugs." (PMID 38468250, 2024). "For empagliflozin, the incidence of DKA was dose-related, and the risk of DKA was associated with concomitant disease or infection with excessive insulin dose reductions or insulin pump failure." (PMID 39957850, 2024). "Oral nanoformulations for insulin uptake via the gut represent a long-sought alternative to subcutaneous injections, which cause pain, discomfort, and possible local infection." (PMID 39000136, 2024). "Although any acute illness or physiological stress can precipitate DKA and HHS, the most frequent causes are infection, particularly urinary tract infections and pneumonia, and the omission of insulin therapy." (PMID 38907161, 2024). "There are a number of reasons for this consideration based on known infection-caused decreases in insulin secretion or increases in insulin resistance during an acute SARS-CoV-2 infection." (PMID 38787222, 2024). "We selected pathways related to metabolism, reproductive disorders, and insulin to study the interaction network of DEPs after PCVL264 infection based on the transcriptomic and proteomic association analysis results for PCVL264 at 7 and 28 dpi." (PMID 40303782, 2023). "An insulin dependent diabetic Charcot patient with Haemoglobin A1C more than 7% has a higher risk of postoperative infection." (PMID 37064618, 2023). "Apart from its invasiveness, the long-term consequences of insulin injection cause the development of physical trauma, which includes lipohypertrophy at the site of administration, scarring, infection, and sometimes nerve damage." (PMID 36979643, 2023). "In contrast, there is evidence that repeated reuse of insulin needles increases the risk of infection." (PMID 37828591, 2023). "Precipitating causes of DKA included infection (14/54; 26%), insulin disruption (14/54; 26%) and betamethasone administration (10/54; 19%)." (PMID 38047210, 2023). "hsa-miR-21-5p plays a role in lipid and insulin metabolism in HCC associated with CHCV-G4 infection cases." (PMID 36834570, 2023). "We also measured the impact of the infection on metabolic parameters, such as adiponectin and leptin, predominant cytokines produced by AT, and insulin as AT dysfunction has also been associated to the insulin pathway." (PMID 35661814, 2022). "In vitro studies have demonstrated that the hepatitis virus (HCV) infection of human β-cells also leads to hypersecretion of insulin in the initial stages of the infection and that it later causes a reduction in insulin in the β-cells." (PMID 35326383, 2022). "The traditional treatment is the manual injection of insulin to regulate blood glucose; patients experience discomfort, such as pain, and there is a risk of infection." (PMID 36290938, 2022).